NKX2-2 (NK2 homeobox 2)
Description:
Transcriptional activator involved in the development of insulin-producing beta cells in the endocrine pancreas (By similarity). May also be involved in specifying diencephalic neuromeric boundaries, and in controlling the expression of genes that play a role in axonal guidance. Binds to elements within the NEUROD1 promoter (By similarity).
Synonyms: NKX2.2; NKX2B
Tractability: PROTAC: ubiquitination databases record sites on it.
Gene: Protein-coding gene on chromosome 20 (21,511,017 to 21,514,064, reverse strand). Ensembl gene ENSG00000125820.
Subcellular location: Nucleus
Pathways (Reactome):
Developmental Biology: Regulation of gene expression in beta cells; Regulation of gene expression in endocrine-committed (NEUROG3+) progenitor cells
Gene Ontology:
Molecular function: protein binding; cis-regulatory region sequence-specific DNA binding; DNA-binding transcription activator activity, RNA polymerase II-specific; DNA-binding transcription factor activity, RNA polymerase II-specific; RNA polymerase II cis-regulatory region sequence-specific DNA binding; DNA binding; DNA-binding transcription factor activity; sequence-specific DNA binding
Biological process: brain development; cell differentiation; regulation of transcription by RNA polymerase II; optic nerve development; positive regulation of transcription by RNA polymerase II; regulation of DNA-templated transcription; response to glucose; response to progesterone
Cellular component: chromatin; nucleoplasm; nucleus
Genetic constraint (gnomAD): Loss-of-function variants: 8 observed, 22.55 expected, observed/expected ratio (o/e) 0.35, 90% interval 0.21 to 0.64. The upper end of that interval is the gene's LOEUF score, 0.64, which puts it in group 2 of 6, group 1 being the genes least tolerant of losing a copy. Missense variants: 381 observed, 375.34 expected, observed/expected ratio (o/e) 1.02, 90% interval 0.93 to 1.11. Synonymous variants: 217 observed, 178.39 expected, observed/expected ratio (o/e) 1.22, 90% interval 1.09 to 1.36.
Homologues: Orthologues: chimpanzee NKX2-2 (100% identical), mouse Nkx2-2 (98% identical), rabbit NKX2-2 (98% identical), guinea pig NKX2-2 (97% identical), pig NKX2-2 (97% identical), rat Nkx2-2 (97% identical), tropical clawed frog nkx2-2 (84% identical), zebrafish nkx2.2a (84% identical), macaque NKX2-2 (75% identical), dog NKX2-2 (74% identical), Drosophila melanogaster scro (38% identical), Caenorhabditis elegans ceh-24 (28% identical), and 5 more. Paralogues in human: NKX2-4 (40% identical), NKX2-8 (40% identical), NKX2-1 (38% identical), NKX2-3 (34% identical), NKX2-5 (33% identical), NKX2-6 (32% identical), NKX3-2 (27% identical), NKX1-1 (24% identical), NKX1-2 (21% identical), NKX3-1 (21% identical), NKX6-2 (18% identical), NKX6-1 (18% identical), and 1 more.
Diseases named in the same sentence as NKX2-2 in open-access papers:
NKX2-2 is named in the same sentence as 77 diseases in open-access papers, as found by Europe PMC text mining. Sharing a sentence is not in itself a finding about the gene and the disease. The quoted sentences say what the papers report.
Ewing sarcoma (57 papers, 2008 to 2026). A small round cell tumor that lacks morphologic, immunohistochemical, and electron microscopic evidence of neuroectodermal differentiation. "By repressing differentiation-associated genes, NKX2-2 helps to sustain the undifferentiated and proliferative state of Ewing sarcoma cells." (PMID 37894854, 2023). "As example, the transcription factors NR0B1 and NKX2-2 are well-known to be associated with Ewing Sarcoma." (PMID 33924679, 2021). "Up-regulation of IFI44L is associated with melanoma and prostate cancer while overexpression of NKX2-2 is associated with Ewing’s sarcoma and fibromatosis." (PMID 27144453, 2016). "However, in Ewing sarcoma, the overexpression of NKX2-2 leads to the repression of genes associated with cellular differentiation." (PMID 37894854, 2023). "Importantly, NKX2-2 was shown to be a sensitive and specific diagnostic marker of Ewing sarcoma versus other look-alike small round blue-cell tumors (SRBCTs), both at the RNA and protein levels." (PMID 26000096, 2015). "In Ewing sarcoma, oncogenic transcription factor NKX2-2 (NK2 homeobox 2) transactivates KIAA1429 expression." (PMID 39456252, 2024). "Due to its distinctive expression pattern in Ewing tumors, several studies have indicated that NKX2-2 serves as a valuable immunohistochemical marker for the detection of Ewing sarcoma." (PMID 37894854, 2023). "Of the 119 molecules found in common, 40 were oncogenes, including 2 Ewing sarcoma specific genes—namely, the NK2 Homeobox 2 (NKX2) and FEV transcription factor (FEV)." (PMID 37444135, 2023). "Instead of acting as a transcriptional activator, NKX2-2 functions as an oncogenic driver in Ewing sarcoma by repressing the expression of genes involved in cell differentiation and promoting a stem-like state." (PMID 37894854, 2023). "The nuclear receptor NR0B1 and the homeobox transcription factor NKX2-2 were up-regulated in Ewing’s sarcoma." (PMID 36194562, 2022). "In fact, the shared changes account for almost half of all changes in every RNA-Seq of CRC TFs, strongly suggesting that KLF15, TCF4 and NKX2-2 coordinate to regulate the transcriptome of Ewing sarcoma cells." (PMID 33080033, 2020). "Phenotypically, similar to CRC factors in other cancer types, KLF15, TCF4 and NKX2-2 each shows strong pro-growth and pro-survival functions in Ewing sarcoma." (PMID 33080033, 2020). "Here, we identify and functionally validate a CRC ‘trio’ constituted by three transcription factors (TFs): KLF15, TCF4 and NKX2-2, in Ewing sarcoma cells." (PMID 33080033, 2020). "This is plausible given that KLF15 almost always cooperates with TCF4 and NKX2-2 in Ewing sarcoma in terms of genomic binding." (PMID 33080033, 2020). "NKX2-2 is an oligodendroglial and astrocytic lineage marker, and also a useful immunohistochemical marker for Ewing sarcoma." (PMID 33179733, 2020). "Considering the prominent roles of CRC in controlling transcriptional network, we postulated that KLF15, TCF4 and NKX2-2 are required for the viability and proliferation of Ewing sarcoma cells." (PMID 33080033, 2020). "Some scholars found that NKX2-2 contributes to oncogenic transformation in Ewing's sarcoma, while downregulation of NKX2-2 correlates with increased tumor malignancy in glioblastoma 21-22." (PMID 32626526, 2020). "In Ewing sarcoma, NKX2-2 is a critical activated target of the oncogenic transcription factor EWS/FLI that is required for transformation." (PMID 26000096, 2015). "Our current work fills in this gap and identifies the importance of NKX2-2 as a tool of EWS/FLI in repressing salient mesenchymal characteristics of Ewing sarcoma cells, first displayed by unbiased transcriptional profiling." (PMID 26000096, 2015). "In Ewing sarcoma, we demonstrated that NKX22 is necessary for the maintenance of transformation in vitro and in vivo." (PMID 26000096, 2015).
Ewing sarcoma (continued). "Since Ewing sarcoma cells form more focal adhesions upon depletion of NKX2-2, we reasoned that they also adhere more effectively to the substrate." (PMID 26000096, 2015). "To this end we knocked down NKX2-2 expression in the Ewing sarcoma cell line A673 using retrovirally delivered shRNA." (PMID 26000096, 2015). "NKX2-2 is upregulated in Ewing sarcoma due to the presence of the EWS/FLI1 fusion protein." (PMID 37894854, 2023). "NKX2-2 plays a role in maintaining a stem-like state in Ewing sarcoma cells." (PMID 37894854, 2023). "In order to address this hypothesis, we modified a computational algorithm given the central role of EWS-FLI1, and identified a CRC ‘trio’ constituted by KLF15, TCF4 and NKX2-2 in Ewing sarcoma cells." (PMID 33080033, 2020). "Taken together, these results demonstrate that as CRC members, KLF15, TCF4 and NKX2-2 may positively co-regulate each other and promote the growth and survival of Ewing sarcoma cells." (PMID 33080033, 2020). "A previous study showed that NKX2-2 silencing suppressed xenograft growth of Ewing sarcoma." (PMID 33080033, 2020). "In addition to cooperating with EWS-FLI1 to co-amplify their own transcription through a CRC model, KLF15, TCF4 and NKX2-2 also exhibit prominent capability of co-regulating the epigenome of Ewing sarcoma cells." (PMID 33080033, 2020). "Interestingly, using a dataset in a recent study of Ewing sarcoma patients from the Children's Oncology Group, we found that below-median expression of NKX2-2 correlates with decreased event-free survival (p = 0.07)." (PMID 26000096, 2015). "The de-repression of ZYX might partially explain how NKX2-2 or EWS/FLI knockdown allows Ewing sarcoma cells to manifest mesenchymal characteristics." (PMID 26000096, 2015). "Thus, the ZEB2 transcriptional profile which represents an “epithelialized” Ewing sarcoma, and the NKX2-2 transcriptional profile which represents a “mesenchymalized” Ewing sarcoma, antagonize each other." (PMID 26000096, 2015). "This suggested that NKX2-2 may contribute to EWS/FLI-mediated impairment of mesenchymal features of Ewing sarcoma cells, which was previously reported." (PMID 26000096, 2015). "Since it is a member of the NK family of homeobox-binding transcription factors and has been demonstrated to control gene expression in many developmental contexts, we reasoned that NKX2-2 depletion and transcriptional profiling would best reveal its function in Ewing sarcoma." (PMID 26000096, 2015). "Indeed, NKX2-2 has been established as a tumor-promoting factor in Ewing sarcoma, but the functions of KLF15 and TCF4 remained hitherto unknown in this cancer." (PMID 33080033, 2020). "Indeed, NKX2-2 has been reported to promoting cell proliferation of Ewing sarcoma, however, the biological significance of either KLF15 or TCF4 had hitherto been unknown in this cancer." (PMID 33080033, 2020). "In Ewing sarcoma, a CRC including KLF15, TCF4, and NKX2-2 MTFs that cooperate with EWSR1::FLI1 was reported in A-673 and EW-8 cells." (PMID 41444391, 2025). "Data 5), we selected six MTFs (TCF12, SOX6, POU3F1, POU3F2, NKX2-2, and IKZF2) as putative members of the Ewing sarcoma CRC, based on fulfilling at least two out of these three criteria." (PMID 41444391, 2025). "The KIAA1429-mediated m6A network facilitates Ewing sarcoma cell proliferation and tumorigenesis via the STAT3 pathway and is regulated by NKX2-2." (PMID 37759224, 2023). "In 2006, NKX2-2 was identified as a gene regulated by EWS/FLI1 and was found to be crucial for the oncogenic transformation in Ewing sarcoma." (PMID 37894854, 2023). "Consistent with mRNA expression, silencing EWS-FLI1 decreased protein level of KLF15, NKX2-2 and TCF4 in Ewing sarcoma cell lines." (PMID 33080033, 2020). "On the other hand, RREB1-silencing did not produce these co-regulatory effects, demonstrating that in Ewing sarcoma cells, KLF15, TCF4 and NKX2-2 together constitute an inter-connected circuitry." (PMID 33080033, 2020).
Ewing sarcoma (continued). "dTAGV-1 led to a decrease in downstream EWS/FLI targets such as NKX2-2, and Gene Set Enrichment Analysis (GSEA) of the differentially regulated target proteins (FDR < 0.05) identified known EWS/FLI and Ewing sarcoma signatures." (PMID 32948771, 2020). "Formed by KLF15, TCF4 and NKX2-2, this CRC apparatus coordinates the gene expression programs, including lipid metabolism, PI3K/AKT and MAPK signaling pathways, in Ewing sarcoma cells." (PMID 33080033, 2020). "This approach generated a total of 147 genes, containing a number of known Ewing sarcoma oncogenes such as CCND1, NKX2–2, BCL11B and MYC." (PMID 30496486, 2019). "Previously, another EWSR1-FLI1 target gene, NKX2-2, was proposed to serve in combination with CD99 as a useful immunohistochemical marker for Ewing sarcoma." (PMID 29416716, 2018). "Strikingly, vorinostat treatment completely reverses the transcriptional profile of NKX2-2, suggesting that NKX2-2 represses genes via modification of histone acetyl-lysine marks in Ewing sarcoma cells." (PMID 26000096, 2015). "Strikingly, we found that EWS/FLI-and NKX22-repressed genes are activated by ZEB2, which was previously shown to block Ewing sarcoma epithelialization." (PMID 26000096, 2015). "We therefore propose that EWS/FLI, through upregulation of NKX2-2, and ZEB2 act to repress differentiation in opposite directions along the epithelial-mesenchymal spectrum; together, they maintain Ewing sarcoma cells in a partially differentiated state." (PMID 26000096, 2015). "A CRC comprising TCF4, NKX2-2, and KLF15 was previously reported in Ewing sarcoma." (PMID 41444391, 2025). "More recent studies have unveiled that NKX2-2, in conjunction with EWSR1-FLI1, binds to the promoter region of STEAP1 (six transmembrane epithelial antigen of the prostate 1), a gene crucial for the survival of Ewing sarcoma." (PMID 37894854, 2023). "NKX2–2, a homeodomain transcription factor involved in neuroendocrine/glial differentiation and a downstream target of EWSR1-FLI1, has been reported as an immunohistochemical marker for Ewing sarcoma." (PMID 33924679, 2021). "Taken together, these data demonstrate that KLF15, TCF4 and NKX2-2 coordinately promote the transcription of chief components of the PI3K/AKT and MAPK signaling pathways, thereby activating these pro-growth and pro-survival signaling cascades in Ewing sarcoma." (PMID 33080033, 2020). "In Ewing sarcoma, the mechanism of action of NKX2-2 is distinct from its normal developmental role." (PMID 37894854, 2023). "Moreover, it also supports our previous data showing that NKX2-2 is necessary but not sufficient for the transformation of Ewing sarcoma cells." (PMID 26000096, 2015). "Similarly, another report showed that NKX2-2 is not fully specific for Ewing sarcoma." (PMID 29416716, 2018). "Furthermore, Ewing sarcoma cells overexpressing AES (amino enhancer of split), a dominant-negative Gro/TLE protein, or treated with the HDAC inhibitor vorinostat display diminished transformation, consistent with NKX2-2 recruitment of Gro/TLE co-repressors and HDACs." (PMID 26000096, 2015).
diabetes (11 papers, 2015 to 2024). "The neonatal diabetes gene with the highest proportion of significant dDMPs was NKX2-2 encoding homeobox protein NKX2-2, a crucial islet transcription factor." (PMID 38831310, 2024). "Bi-DOCS were associated with genes related to pancreas development and beta-cell function, including transcription factors mutated in monogenic diabetes (PDX1, NKX2-2, HNF1A; FDR < 0.05)." (PMID 29107594, 2017). "Importantly however, bi-allelic null variants in NKX2-2 cause neonatal diabetes and the parents, who are heterozygous carriers, do not have hypoglycaemia." (PMID 38605124, 2024). "In addition to NKX6–1 we found variants in WFS1, RFX6 and 7 other genes associated with monogenic forms of diabetes (AKT2, EIF2AK3, GLIS3, HADH, MNX1, NKX2–2, and PTF1A) and they may be relevant to development of MODY." (PMID 29439679, 2018).
sarcoma (10 papers, 2020 to 2025). A usually aggressive malignant neoplasm of the soft tissue or bone. "While FLI1 is unable to confirm EwS cases with FET–non-FLI1 translocations, NKX2-2 and PAX7 lack specificity and can be even strongly expressed in close morphological mimics such as EWSR1-NFATc2-positive sarcomas." (PMID 32164354, 2020). "The downstream target of EWSR1-FLI1, NKX2-2, is expressed in virtually all ES but is negative in CIC rearranged sarcomas." (PMID 32155762, 2020).
glioma (6 papers, 2010 to 2025). A benign or malignant brain and spinal cord tumor that arises from glial cells (astrocytes, oligodendrocytes, ependymal cells). "The analysis of genes specifically downregulated at relapse after radiotherapy identified NKX2-2, a transcription factor involved in glioma histogenesis." (PMID 20885975, 2010). "Proneural glioma are defined by the expression of the neurogenesis markers PDGFRA, NKX2-2, and OLIG2, and they are IDH1 mutants." (PMID 35328529, 2022).
rhabdomyosarcoma (6 papers, 2015 to 2025). A rare aggressive malignant mesenchymal neoplasm arising from skeletal muscle. "Although newer markers such as NK2 homeobox 2 (NKX2.2) have been shown to improve diagnostic specificity, particularly in distinguishing ES from other small round cell tumors, including lymphoma and rhabdomyosarcoma, these studies were not available at our institution." (PMID 41589178, 2025). "Further GSEA analyses indicated that the NKX22-regulated genesets are not enriched in transcriptional profiles of rhabdomyosarcomas driven by PAX-FKHR fusions (data not shown)." (PMID 26000096, 2015).
osteosarcoma (5 papers, 2020 to 2024). A usually aggressive malignant bone-forming mesenchymal neoplasm, predominantly affecting adolescents and young adults. "Moreover, overexpression of COL5A2 has been related to worse prognosis with potential association with invasion and dissemination in bladder carcinoma, or in osteosarcoma, as an effector of NKX2-2, among others." (PMID 33066614, 2020). "Moreover, overexpression of NKX2-2 decreased the migration, invasion, proliferation and colony formation of osteosarcoma cells in vitro and suppressed tumor growth and metastasis in vivo." (PMID 32626526, 2020).
breast carcinoma (3 papers, 2020 to 2024). "As potential transcription factors regulating the expression of ERBB2, MNX1 and NKX2-2 emerged as the highest-expressed in HER2-E breast cancer, followed by Luminal B breast cancer." (PMID 38339428, 2024). "However, the role of NKX2-2 in breast cancer has not been revealed." (PMID 33179733, 2020).
glioblastoma (3 papers, 2015 to 2022). The most malignant astrocytic tumor (WHO grade IV). "The methylation of NKX2-2 was identified as part of a signature for glioblastoma multiforme." (PMID 26039411, 2015).
Hodgkins lymphoma (3 papers, 2018 to 2019). A heterogeneous group of malignant lymphoid neoplasms of B-cell origin characterized histologically by the presence of Hodgkin and Reed-Sternberg (HRS) cells in the vast majority of cases. "Recently, ectopic expression of NKX2-2 has been described in Hodgkin lymphoma, indicating oncogenic functions in both B- and T-lymphocytes." (PMID 31143370, 2019). "Here, we introduce the NKL-code in normal hematopoiesis and focus on deregulated NKL homeobox genes in B-cell lymphoma, including HLX, MSX1 and NKX2-2 in Hodgkin lymphoma; HLX, NKX2-1 and NKX6-3 in diffuse large B-cell lymphoma; and NKX2-3 in splenic marginal zone lymphoma." (PMID 31779217, 2019). "Here, we identified aberrant expression of the non-hematopoietic neural NKL homeobox gene NKX2-2 in about 12% of both, classical Hodgkin lymphoma (HL) and nodular lymphocyte predominant (NLP) HL patients." (PMID 30680064, 2018).
Hyperglycemia (3 papers, 2015 to 2023). An increased concentration of glucose in the blood. "Nkx2-2 mutant mice became diabetic after birth and died due to the hyperglycemia." (PMID 26082830, 2015).
insulinoma (3 papers, 2014 to 2021). "βlinc1 knockdown in mouse insulinoma cells (MIN6) resulted in down-regulation of Nkx2-2, indicating the lncRNA is a positive regulator of Nkx2-2 expression, although the mechanism is unknown." (PMID 34581756, 2021).
melanoma (3 papers, 2016 to 2024). A malignant, usually aggressive tumor composed of atypical, neoplastic melanocytes. "Male-specific DEGs include MCM7, a DNA replication licensing factor; NKX2-2, an important biomarker for metastatic prostate cancers; and NGFR, the canonical single-pass transmembrane receptor linked to melanoma and squamous cell carcinoma." (PMID 35158998, 2022).